TSPAN6 (tetraspanin 6)
Diseases named in the same sentence as TSPAN6 in open-access papers (continued):
Sharing a sentence is not in itself a finding about the gene and the disease.
glioblastoma (1 paper, 2024). The most malignant astrocytic tumor (WHO grade IV). "The presence of TSPAN6 was positively associated with cancer stem cell-like properties in glioblastoma." (PMID 38725860, 2024). "In addition, the presence of TSPAN6 was positively associated with cell cycle of glioblastoma cells." (PMID 38725860, 2024). "More interestingly, TSPAN6 overexpression in glioblastoma cells promoted angiogenesis via enhancing the migrative ability of vascular endothelial cells in TME." (PMID 38725860, 2024). "In contrast, glioblastoma cells with a high level of TSPAN6 enhanced the migrative ability of the vascular endothelial cells." (PMID 38725860, 2024). "Meanwhile, TSPAN6 siRNA significantly restrained cell proliferation of glioblastoma compared with control siRNA." (PMID 38725860, 2024). "In contrast, TSPAN6 overexpression promoted the activation of STAT3 via enhancing the phosphorylating STAT3 in glioblastoma cells." (PMID 38725860, 2024). "Glioblastoma cells with low level of TSPAN6 statistically reduced the migrative ability of HUVEC cells by regulating TME." (PMID 38725860, 2024). "Knockdown of TSPAN6 significantly suppressed the migratory ability of glioblastoma cells using transwell assay." (PMID 38725860, 2024). "Mechanistically, TSPAN6 enhanced the malignant progression of glioblastoma by interacting with CDK5RAP3 and regulating STAT3 signaling pathway." (PMID 38725860, 2024). "GSEA analysis demonstrated that the expression of TSPAN6 was positively correlated with protein transmembrane transport in glioblastoma." (PMID 38725860, 2024). "In contrast, TSPAN6 overexpressing glioblastoma cells reinforced the expression of VEGFR2 in HUVEC cells compared with empty vector transfected glioblastoma cells." (PMID 38725860, 2024). "Meanwhile, glioblastoma patients with high level of TSPAN6 had shorter overall survival compared with low level of TSPAN6." (PMID 38725860, 2024). "STAT3 inhibition suppressed the enhanced migrative ability induced by glioblastoma cells overexpressing TSPAN6 in HUVEC cells." (PMID 38725860, 2024). "Collectively, this work firstly declared that TSPAN6 was overexpressed in glioblastoma and TSPAN6 overexpression predicted poor outcome of glioblastoma patients." (PMID 38725860, 2024). "Meanwhile, TSPAN6 and STAT3 were both mostly overexpressed in endothelial cells of glioblastoma, and the colocalization of TSPAN6 and STAT3 was verified in endothelial cells by single cell sequencing." (PMID 38725860, 2024). "In contrast, TSPAN6 overexpression significantly enhanced the migratory ability of glioblastoma cells." (PMID 38725860, 2024). "More importantly, we also determined the expression of TSPANs in glioblastoma and normal tissues, among all the TSPANs, TSPAN6 was mostly overexpressed in glioblastoma comparing to normal tissues." (PMID 38725860, 2024). "Collectively, TSPAN6 has the potential to serve as both a therapeutic target and a prognostic biomarker for the treatment of glioblastoma." (PMID 38725860, 2024). "Meanwhile, STAT3 inhibitor niclosamide suppressed the enhanced migrative ability induced by glioblastoma cells overexpressing TSPAN6 in HUVEC cells." (PMID 38725860, 2024). "Indeed, exosome secretion inhibitor reversed the migrative abilities of vascular endothelial cells enhanced by TSPAN6 overexpressing glioblastoma cells." (PMID 38725860, 2024). "In this study, we hypothesized that TSPAN6 might promote the biogenesis of exosomes via STAT3 pathway in glioblastoma cells, and subsequently regulate angiogenesis in TME by STAT3." (PMID 38725860, 2024). "In addition, TSPAN6 overexpression in glioblastoma cells enhanced angiogenesis via regulating TME and STAT3 signaling pathway." (PMID 38725860, 2024). "TSPAN6 knockdown statistically inhibited the activation of STAT3 in glioblastoma cells." (PMID 38725860, 2024). "In addition, TSPAN6 interacted with CDK5 kinase regulatory-subunit associated protein 3 (CDK5RAP3) and regulated STAT3 signaling pathway in glioblastoma." (PMID 38725860, 2024).
glioblastoma (continued). "Meanwhile, wound healing assay also demonstrated that TSPAN6 silence could restrain the migrative ability of glioblastoma cells." (PMID 38725860, 2024). "In addition, STAT3 inhibitor niclosamide successfully reversed TSPAN6 activated EMT progress of glioblastoma cells." (PMID 38725860, 2024). "Furthermore, TSPAN6 suppression significantly restrained the colony formation of glioblastoma cells." (PMID 38725860, 2024). "In vivo tail vein injection model also confirmed that TSPAN6 knockdown could reduce glioblastoma cells metastasize to lung." (PMID 38725860, 2024). "We firstly determined that TSPAN6 acted as an oncogenic gene in glioblastoma progression." (PMID 38725860, 2024). "Furthermore, TSPAN6 promoted the malignant progression of glioblastoma via promoting the proliferation and metastatic potential of glioblastoma cells." (PMID 38725860, 2024). "Furthermore, TSPAN6 promoted the malignant progression of glioblastoma by interacting with CDK5RAP3 and regulating STAT3." (PMID 38725860, 2024). "Furthermore, TSPAN6 siRNA statistically restrained the invasive ability of glioblastoma cells compared to control siRNA." (PMID 38725860, 2024). "Furthermore, CDK5RAP3 knockdown successfully reversed the enhanced migrative and invasive abilities induced by TSPAN6 overexpression in glioblastoma cells." (PMID 38725860, 2024). "Meanwhile, the immunohistochemistry results also supported that TSPAN6 could coexpress with stem cell marker Sox2 and division marker Ki67 (r = 0.86, p<0.0001) in glioblastoma tissues." (PMID 38725860, 2024). "Indeed, glioblastoma cells with high level of TSPAN6 statistically enhanced STAT3 activation of HUVEC cells." (PMID 38725860, 2024). "Thus, TSPAN6 promotes cancer progress by STAT3 signaling pathway in glioblastoma cells, and TSPAN6 also regulates angiogenesis via exosome through STAT3 pathway in TME." (PMID 38725860, 2024). "Meanwhile, STAT3 knockdown also reversed TSPAN6 activated EMT progress of glioblastoma cells." (PMID 38725860, 2024). "But the function of TSPAN6 on glioblastoma development is still poorly understood." (PMID 38725860, 2024). "Moreover, CDK5RAP3 knockdown could efficiently reverse TSPAN6-induced STAT3 activation in glioblastoma cells." (PMID 38725860, 2024). "Thus, TSPAN6 is also regarded as a therapeutic target to regulate TME of glioblastoma, and the significance of TSPAN6 in cancer progress may provide clues for the diagnosis and treatment of glioblastoma." (PMID 38725860, 2024). "Thus, glioblastoma cells overexpressing TSPAN6 may induce STAT3 activation of vascular endothelial cells and promote angiogenesis in TME of glioblastoma." (PMID 38725860, 2024). "Thus, TSPAN6 reinforces the metastatic potential of glioblastoma cells." (PMID 38725860, 2024). "Besides, TSPAN6 promoted the angiogenesis of glioblastoma via regulating TME." (PMID 38725860, 2024). "Meanwhile, glioblastoma cells with TSPAN6 knockdown also decreased the migrative ability of vascular endothelial cells using the wound healing assay, and glioblastoma cells with TSPAN6 overexpression enhanced the migrative ability of vascular endothelial cells." (PMID 38725860, 2024). "In addition, the overexpression of TSPAN6 reinforced the invasion of glioblastoma cells." (PMID 38725860, 2024). "Furthermore, TSPAN6 reinforced the cell proliferative ability and metastatic potential of glioblastoma cells, indicating that TSPAN6 might be a potential therapeutics target for glioblastoma." (PMID 38725860, 2024). "Thus, TSPAN6 might be involved in the proliferation of glioblastoma cells." (PMID 38725860, 2024). "This study demonstrated that TSPAN6 enhanced the phosphorylation of STAT3 in glioblastoma cells, CDK5RAP3 knockdown reversed TSPAN6-activated STAT3, indicating that TSPAN6 activated STAT3 via CDK5RAP3 in glioblastoma cells." (PMID 38725860, 2024). "Thus, TSPAN6 might promote metastatic potential and angiogenesis of glioblastoma via exosomes." (PMID 38725860, 2024).
glioblastoma (continued). "The migration of HUVEC cells was detected when those cells were co-cultured with glioblastoma cells treated with negative siRNA and TSPAN6 siRNA." (PMID 38725860, 2024). "In addition, TSPAN6 induced STAT3 activation of vascular endothelial cells and promoted angiogenesis in TME of glioblastoma." (PMID 38725860, 2024). "To explore the mechanism of TSPAN6 in promoting angiogenesis in TME, we hypothesized that glioblastoma cells overexpressing TSPAN6 might induce STAT3 activation of vascular endothelial cells." (PMID 38725860, 2024). "Furthermore, TSPAN6 elicited the progress of EMT via downregulation of N-cadherin and upregulation of E-cadherin and Vimentin in glioblastoma cells." (PMID 38725860, 2024). "After treated with GW4869 to restrain the exosomes release, glioblastoma cells with TSPAN6 overexpression failed to enhance the migrative ability of vascular endothelial cells." (PMID 38725860, 2024). "Furthermore, the immunohistochemistry results also supported that TSPAN6 was overexpressed in glioblastoma tissues compared with normal tissues (p = 0.0034)." (PMID 38725860, 2024). "Furthermore, TSPAN6 interacted with CDK5RAP3 and promoted the progress of glioblastoma." (PMID 38725860, 2024). "Furthermore, TSPAN6-knockdown glioblastoma cells significantly suppressed the level of VEGFR2 in HUVEC cells compared with negative control siRNA transfected glioblastoma cells." (PMID 38725860, 2024). "Thus, we assumed that TSPAN6 might interact with CDK5RAP3 and enhance the progress of glioblastoma via STAT3." (PMID 38725860, 2024). "So far, the function of TSPAN6 in glioblastoma development has not been elucidated." (PMID 38725860, 2024). "Thus, TSPAN6 may interact with CDK5RAP3 and promote metastatic potential of glioblastoma cells." (PMID 38725860, 2024).
intestinal tumor (1 paper, 2023). "Tetraspanin 6 (Tspan6), frequently downregulated in CRC, proved to suppress early stages of intestinal tumor development in APCMin/+ mice." (PMID 36831450, 2023).
metastatic tumor (1 paper, 2024). "On the other hand, CD9, TSPAN6, and TSPAN8 were downregulated in the tumor compartment of metastatic tumor." (PMID 38255741, 2024). "Conversely, CD9, TSPAN6, and TSPAN8 were downregulated in the tumor compartment of metastatic tumor." (PMID 38255741, 2024).
pancreatic adenocarcinoma (1 paper, 2022). "Importantly, low TSPAN6 expression also significantly correlated with poor survival in these pancreatic adenocarcinoma cohorts (p = 0.028 for GSE17891 and p = 0.001 for GSE11838)." (PMID 35184157, 2022).
prostate carcinoma (1 paper, 2015). A carcinoma that arises from epithelial cells of the prostate gland. "Several tetraspanins such as CD81, CD9, tetraspanin-6 and tetraspanin-8 were enriched in prostate cancer versus control samples." (PMID 26196085, 2015). "Other proteins enriched in prostate cancer proteins such as LAPTM4A, RAB7A, AFAP, and TSPAN6 are putative targets for CRL1 as detected by screening with a NEDD8 activating enzyme inhibitor." (PMID 26196085, 2015).
spina bifida (1 paper, 2020). A congenital neural tube defect in which vertebrae are not fully formed. "As a member of the tetraspanin family, tetraspanin-6 (TSPAN6) was predicted to be co-regulated by miR-142-3p and miR-144 in spina bifida." (PMID 33343629, 2020). "In this study, we identified a miRNA–mRNA regulatory network including four miRNAs and 39 mRNAs in spina bifida and implicate TSPAN6, YOD1, and KCND3, ubiquitylation pathways, and an antiviral immune response as modulators of neural tube malformations." (PMID 33343629, 2020). "TSPAN6 may be tractable as a therapeutic target for spina bifida based on the results obtained from a literature search and data analysis." (PMID 33343629, 2020).
X-linked intellectual disability (1 paper, 2017). An X-linked intellectual deficiency in which not enough information is known, reported or published to indicate whether a gene causes non-syndromic or syndromic presentations. "In fact, Tspan7, homologous to Tspan6 and associated with X-linked intellectual disability, has been described to play a role in synapse development in vitro." (PMID 28207852, 2017). "Interestingly, mutations in Tspan7, highly homologous to Tspan6, are associated with X-linked intellectual disability, suggesting that these two proteins are important for cognition." (PMID 28207852, 2017).
tumor (13 papers, 2017 to 2026). "Using the Cancer Immunology Data Engine (CIDE) covering 5,957 patients across 17 tumor types, TSPAN6 was identified as significantly associated with adverse immunotherapy outcomes." (PMID 41782878, 2026). "Whole-body knockout as well as tumor cell autonomous inactivation using floxed alleles of Tspan6 in mice enhanced KrasG12D-driven lung tumor initiation and malignant progression." (PMID 35184157, 2022). "TSPAN6 has been associated with tumor cell migration, and over-expression is linked to worsened survival in CRC patients." (PMID 28455965, 2017). "Western blotting of tumor tissue confirmed efficient loss of Tspan6 in Tspan6fl/yKrasG12D mice." (PMID 35184157, 2022). "Additionally, our results indicate that loss of Tspan6 results in enhanced epithelial proliferation and altered epithelial architecture implicated in cell morphology, migration and tumor invasion/metastasis." (PMID 35184157, 2022). "Few studies have investigated the function of TSPAN6 in HCC; until recently, a study suggests TSPAN6 may associate with the aggregates of CD20+ B cells in tumor." (PMID 34540692, 2021). "Spatial transcriptomics further demonstrated TSPAN6 enrichment in tumor cores and its significant downregulation in immunotherapy responders compared to non-responders." (PMID 41782878, 2026). "Genetic ablation of TSPAN6 in co-culture models enhanced anti-tumor immunity, functionally validating this mechanism." (PMID 41782878, 2026). "Altogether, our results reveal TSPAN6 as a novel tumor suppressor gene that cooperates with activated RAS." (PMID 35184157, 2022). "Quantification of overall tumor burden revealed a significant increase of the tumor areas in the lungs of Tspan6−/yKrasG12D mice compared to Tspan6+/yKrasG12D littermates." (PMID 35184157, 2022). "Survival analysis conducted for 1926 NSCLC patients revealed a significant correlation (p = 0.0008) between low TSPAN6 tumor expression and reduced patient survival." (PMID 35184157, 2022). "Our study has revealed a novel role for the Tetraspanin TSPAN6 as a tumor suppressor in Ras-driven cancer." (PMID 35184157, 2022). "Selective loss of Tspan6 in the KrasG12D-expressing lung epithelial cells again resulted in significantly reduced survival and increased tumor burden as compared to Tspan6-expressing KrasG12D littermates." (PMID 35184157, 2022). "Stable knockdown of Tspan6 in Ras-transformed EpRas cells indeed enhanced tumor growth in vivo following orthotopic injection." (PMID 35184157, 2022). "TSPAN6 expression indeed differentiated between the EMT and epithelial NSCLC tumor subgroups, with high TSPAN6 expression being associated with an epithelial signature, which correlates with better therapy response and overall patient survival." (PMID 35184157, 2022). "Further delineation of the molecular composition of the Tspan6-syntenin-1–centered protein network will provide a more comprehensive view as to how Tspan6 can affect the tumor microenvironment in CRC and other types of cancer." (PMID 34521767, 2021). "It is also possible that the contribution of the TGF-α−EGFR signaling pathway (and, therefore, Tspan6) to the development of the malignant phenotype involves other cell types in the tumor microenvironment." (PMID 34521767, 2021). "The other member TSPAN6 could suppress tumor growth and metastasis of human RAS activating mutant pancreatic cancer xenografts." (PMID 36941633, 2023).
tumor (continued). "The reduced clonogenic growth of MDA-MB-231 herein may be attributed to the upregulation of some tumor suppressor proteins such as TSPAN6, MAPK6, SPRY2, HAUS4, stomatin (STOM) and conserved oligomeric golgi complex subunit 8 (COG8)." (PMID 38283944, 2023). "Whether Tsp29Fb/TSPAN6 also regulates aPKC to mediate its tumor suppressor effects remains to be determined." (PMID 35184157, 2022). "Conversely, knockdown of human TSPAN6 in human mammary epithelial cells enhances the oncogenic RAS-driven invasive phenotype, and knockdown of mouse Tspan6 enhances cell proliferation and in vivo tumor growth and metastases of oncogenic Ras-transformed mouse epithelial cells." (PMID 35184157, 2022). "Whether these effects on epithelial architecture modulate EGFR-RAS-ERK activation (perhaps through altering SCRIB/DLG1 function) or affect other signaling pathways to contribute to the tumor suppressor function of Tsp29Fb/TSPAN6 needs to be examined." (PMID 35184157, 2022). "We have also recently demonstrated that Tspan6 regulates the production of exosomes, nanovesicles that contribute to both autocrine regulation of cancer cell proliferation and paracrine communication between various cells within the tumor microenvironment." (PMID 34521767, 2021). "Importantly, the expression of Tspan6 in CRC correlated independently of tumor molecular profile with better patient responses to Cetuximab, an EGFR-targeted therapy." (PMID 34521767, 2021). "Thus, the expression of Tspan6 was analyzed by immunohistochemistry in 184 tumor samples from the COIN study." (PMID 34521767, 2021). "Considering our results that TSPAN6 had no apparent effect on EGFR-induced proliferation but markedly altered invasive behavior in response to EGF, TSPAN6-regulated cell polarity and an EMT could conceivably explain why the modulation of TSPAN6 expression affects metastatic tumor spread." (PMID 35184157, 2022). "On the other hand, some TSPAN family members, such as CD82, TSPAN6, TSPAN9 and CD63, exhibit tumor suppressor properties." (PMID 36941633, 2023). "Taken together, our experiments using stable knockdown of endogenous Tspan6 in H-Ras-transformed mouse epithelial cells identify Tspan6 as a regulator of RAS-oncogene dependent epithelial identity, tumor growth, and invasion/metastasis." (PMID 35184157, 2022). "Importantly, knockdown of Tspan6 was sufficient to trigger an EMT in Ras-transformed mouse mammary epithelial cells and in in vivo tumor experiments we also observed an EMT, as defined by altered Vimentin and E-Cadherin expression, in Tspan6 knockdown cells." (PMID 35184157, 2022). "As our results showed that depletion of TSPAN6 in epithelial cells leads to an EMT and tumor progression, we asked whether TSPAN6 expression could be used to differentiate between EMT and epithelial subgroups of NSCLC tumors." (PMID 35184157, 2022). "Thus, we hypothesized that TSPAN6 might be involved in angiogenesis via protein transmembrane transport within TME, and promote tumor growth and metastasis." (PMID 38725860, 2024).